KRT6A (keratin 6A)
Description:
Structural component of intermediate filaments in epithelial keratinocytes. Forms heteropolymers with the type I keratins KRT16 and KRT17, assembling into keratin intermediate filament networks that contributes to the structural integrity and stress resilience of stratified epithelia, particularly in epidermis, nail bed and oral mucosa. Rapidly induced in wound-edge keratinocytes and participates in cytoskeletal reorganization during re-epithelialization (By similarity). Negatively regulates collective keratinocyte migration by stabilizing non-muscle myosin MYH9 and desmoplakin, thereby altering cell-cell and cell-matrix adhesion and reducing the speed and directionality of epithelial sheet movement during wound repair (By similarity). Also limits epithelial migration by inhibiting SRC activity during wound repair (By similarity). Required for normal palmoplantar, nail unit and oral mucosa integrity.
Synonyms: K6A; KRT6D; CK6C; K6C; CK6D; K6D; CK-6C; CK-6E; CK6A; KRT6C; PC3
Tractability: PROTAC: ubiquitination databases record sites on it.
Gene: Protein-coding gene on chromosome 12 (52,487,176 to 52,493,257, reverse strand). Ensembl gene ENSG00000205420.
Subcellular location: Cytoplasm
Subcellular location (Human Protein Atlas): Intermediate filaments
Pathways (Reactome):
Developmental Biology: Formation of the cornified envelope; Keratinization
Gene Ontology:
Molecular function: protein binding; structural constituent of cytoskeleton; structural constituent of skin epidermis
Biological process: antimicrobial humoral immune response mediated by antimicrobial peptide; defense response to Gram-positive bacterium; killing of cells of another organism; negative regulation of entry of bacterium into host cell; cell differentiation; intermediate filament organization; keratinization; morphogenesis of an epithelium; negative regulation of cell migration; positive regulation of cell population proliferation; wound healing
Cellular component: extracellular exosome; intermediate filament cytoskeleton; membrane; nucleus; cytosol; keratin filament; cytoplasm
Genetic constraint (gnomAD): Loss-of-function variants: 28 observed, 50.81 expected, observed/expected ratio (o/e) 0.55, 90% interval 0.41 to 0.75. The upper end of that interval is the gene's LOEUF score, 0.75, which puts it in group 3 of 6, group 1 being the genes least tolerant of losing a copy. Missense variants: 687 observed, 729.9 expected, observed/expected ratio (o/e) 0.94, 90% interval 0.88 to 1. Synonymous variants: 301 observed, 297.75 expected, observed/expected ratio (o/e) 1.01, 90% interval 0.92 to 1.11.
Homologues: Orthologues: mouse Krt6a (86% identical), mouse Krt6b (85% identical), rat LOC100365213 (83% identical), rat LOC120093742 (83% identical), rat Krt6c (82% identical), rat LOC102553726 (80% identical), mouse Gm5414 (70% identical), rat AABR07001416.1 (70% identical). Paralogues in human: KRT6B (99% identical), KRT6C (98% identical), KRT5 (80% identical), KRT75 (72% identical), KRT3 (67% identical), KRT76 (66% identical), KRT1 (63% identical), KRT2 (62% identical), KRT79 (61% identical), KRT4 (59% identical), KRT77 (56% identical), KRT73 (55% identical), and 56 more.
Diseases named in the same sentence as KRT6A in open-access papers:
KRT6A is named in the same sentence as 103 diseases in open-access papers, as found by Europe PMC text mining. Sharing a sentence is not in itself a finding about the gene and the disease. The quoted sentences say what the papers report.
lung carcinoma (24 papers, 2016 to 2025). "Recent studies revealed that high expression of KRT6A is associated with unfavorable prognosis of lung cancer patients." (PMID 34235156, 2021). "Overexpression of KRT6A was associated with a poor prognosis of lung adenocarcinoma, as it promotes proliferation and metastasis of lung cancer via EMT and cancer stem cells transformation." (PMID 34795689, 2021). "The research indicated that KRT6A was associated with lung cancer OS." (PMID 38656878, 2024). "We believed that SRXN1 and KRT6A might be the early diagnostic biomarkers and therapy targets on clinical therapy of smoke cause lung cancer with further validated study in future." (PMID 35071014, 2021). "Besides, cancer-related studies identified associations between the expression of KRT6A and several diseases and cancers, such as pachyonychia congenita, oral squamous cell carcinoma, lung cancer, renal carcinoma and progressive breast cancer." (PMID 35071014, 2021). "Finally, KRT6A is a cytoskeletal scaffolding protein whose increased expression is associated with improved survival in breast cancer but portends a worse prognosis in lung cancer and is associated with squamous differentiation." (PMID 30092011, 2018). "Quantitative PCR and western blotting confirmed increased expression of Srxn1 and KRT6A mRNA and protein in lung cancer cell lines and non‐small cell lung cancer tissues." (PMID 40111164, 2025). "Previous research in ASLC has shown that LSD1, upstream of the highly-expressed KRT6A, promotes KRT6A gene expression, thus facilitating lung cancer cell growth and invasion." (PMID 40568576, 2025). "This study aims to comprehensively investigate the prognostic significance of KRT6A in human lung cancer." (PMID 38656878, 2024). "A recent study showed that KRT6A promotes growth and invasion of lung cancer cells by regulating glucose-6-phosphate dehydrogenase expression through MYC." (PMID 36275729, 2022). "KRT6A is also overexpressed in lung adenocarcinoma and promotes lung cancer cell proliferation, migration, and colony formation ability via epithelial–mesenchymal transition and cancer stem cells transformation." (PMID 35740697, 2022). "Keratin 6A is a type II cytokeratin hyperexpressed keratin 6A in lung adenocarcinoma that promotes lung cancer proliferation and metastasis via epithelial–mesenchymal transition and cancer stem cells transformation." (PMID 34203201, 2021). "Our study demonstrated the relationship between high KRT6A expression and pathological progression of NSCLC, and dissected the molecular mechanism underlying KRT6A regulated invasion of lung cancer cells." (PMID 34235156, 2021). "Quantitative PCR and western blotting validated the increased expression of SRXN1 and KRT6A mRNA and protein, respectively, in lung cancer cell lines and NSCLC tissues." (PMID 35071014, 2021). "To address the functional consequence of KRT6A upregulation in lung cancer, we established H1299 and A549 cells with KRT6A knockdown or overexpression." (PMID 34235156, 2021). "Our results show that depleting KRT6A inhibited cell proliferation of lung cancer cells, and KRT6A overexpression promoted cell proliferation." (PMID 34235156, 2021). "Because SRXN1 and KRT6A expression was upregulated in lung cancers, we designed three siRNAs to suppress the endogenous expression of SRXN1 and KRT6A transcripts." (PMID 35071014, 2021). "To explore the role of KRT6A in lung cancer, we used expression data for KRT6A in lung cancer from The Cancer Genome Atlas (TCGA) database." (PMID 34235156, 2021). "The studies based on proteomic analysis of exhaled breath condensate in the group of patients with lung cancer, in the healthy volunteers and additionally on primary human gingival epithelial cells, showed that KRT6A and KRT6B proteins were elevated in 58.1% of smokers in both groups." (PMID 39000463, 2024).
lung carcinoma (continued). "Besides, cell experiments have shown that when the KRT6A gene is downregulated, the proliferation and invasion ability of lung cancer cells is weakened." (PMID 38656878, 2024). "Additionally, LAMC2 promotes the chemotactic function of granulocytes; DSC2 correlates positively with adhesion, migration, and infiltration of granulocytes; and KRT6A protein inhibits the proliferation, migration and invasion abilities of lung cancer cells." (PMID 36817446, 2023). "KRT6A gene overexpression in LUAD promotes lung cancer cell proliferation by EMT68." (PMID 37592010, 2023). "Evidence has shown carcinogenic effects of KRT6A in lung cancer." (PMID 37315289, 2023). "KRT6A was reported could promote lung cancer cell growth and invasion, it also could serve as invasion-related gene signature predicts prognostic features of LUAD." (PMID 35830566, 2022). "Notably, we identified SRXN1 and KRT6A as pivotal smoking-related genes (SRGs) with important roles in lung cancer carcinogenesis through subsequent experimental validation in vitro and in vivo." (PMID 35071014, 2021). "Furthermore, inhibition of SRXN1 or KRT6A suppressed viability and enhanced apoptosis in the A549 human lung carcinoma cell line." (PMID 35071014, 2021). "In summary, these results suggest that SRXN1 and KRT6A might be potential biomarkers of smoking exposure and early lung cancer diagnosis and prognosis." (PMID 35071014, 2021). "Furthermore, we observed increased expression of SRXN1 and KRT6A mRNA and protein in lung cancer cell lines (95D, A549) and BEAS-2B-NNK cells, compared with normal BEAS-2B cells (both P < 0.05)." (PMID 35071014, 2021). "Therefore, deeper investigations are warranted to explore the function of KRT6A in lung cancer progression." (PMID 34235156, 2021). "In summary, we discovered that KRT6A expression is frequently upregulated in lung cancer." (PMID 34235156, 2021). "Consistently, KRT6A significantly decreases E-cadherin levels in lung cancer cells." (PMID 34235156, 2021). "These previous studies confirm the important roles of SRXN1 and KRT6A in lung cancer." (PMID 35071014, 2021). "More importantly, both SRXN1 and KRT6A expression were significantly correlated with smoking so that we proposed an assumption that SRXN1 and KRT6A might be the key for preventing smoke cause lung cancer." (PMID 35071014, 2021). "For example, KRT5, KRT6A, KRT14, and DSG3 in LUSC25, and NKX2.126, SFTA227 in LUAD have been evidently proved directly correlated to the lung cancer diagnosis and progression." (PMID 40654610, 2025). "KRT6A regulates the pentose phosphate pathway through the MYC pathway, thereby promoting lung cancer cell growth and invasion." (PMID 37315289, 2023). "The high expression of KRT6A protein is related to good prognosis in patients with lung adenocarcinoma; FOSB protein plays an anti-tumor role in lung cancer." (PMID 36817446, 2023). "Results indicated a significant downregulation of CX3CL1, MS4A15, and GSTA1 in lung cancer cells, while EPS8L3, G6PD, KRT6A, and S100P were notably upregulated, in line with the bioinformatics analysis findings." (PMID 37315289, 2023). "KRT6A regulates the expression of G6PD through c-MYC/MYCN to promote the proliferation and invasion of lung cancer cells." (PMID 34235156, 2021). "Here, our study has yielded similar results, by showing that KRT6A is upregulated in NSCLC tumors and promotes lung cancer cell proliferation and invasion in vitro." (PMID 34235156, 2021). "High expression of KRT6A in LUAD may promote the proliferation and metastasis of lung cancer through epithelial‐mesenchymal transformation and cancer cell transformation." (PMID 34060213, 2021). "Prognostic associations of KRT5 and KRT14 have been implicated in lung cancer, while the relationship and molecular mechanisms of KRT6A and KRT17 in the lung cancer are still unknown and should be further elucidated." (PMID 27684953, 2016).
lung carcinoma (continued). "For example, KRT5,KRT6A, KRT14, and DSG3 (All of these genes shown are with an adjustedp-value < 1e–200) in LUSC, and NKX2.1, SFTA2 (All of these genes shown are with anadjusted P-value < 1e–200) in LUAD have beenevidently proved directly correlated to the lung cancer diagnosis andprogression." (PMID 41347120, 2025). "Similarly, KRT6A, MIR31HG, and FOLR1 have been found to enhance lung cancer proliferation and may be potential therapeutic targets." (PMID 38926418, 2024). "Although cytokeratin detection could be due to epidermal contamination, cytokeratins have previously been shown to be the most abundant proteins in EBC30, and both KRT6A and KRT6B have been identified as potential biomarkers for lung carcinomas in EBC proteomic analyses." (PMID 37147394, 2023). "In summary, SRXN1 and KRT6A act as oncogenes in NSCLC and might be potential biomarkers of smoking exposure and the early diagnosis and prognosis of NSCLC in smokers, which is vital for lung cancer therapy." (PMID 35071014, 2021).
lung adenocarcinoma (17 papers, 2011 to 2024). A carcinoma that arises from the lung and is characterized by the presence of malignant glandular epithelial cells. "Elevated levels of keratin 6A in lung adenocarcinoma have been associated with a poorer patient prognosis, promoting growth and metastasis." (PMID 38612418, 2024). "In lung adenocarcinoma, a high KRT6A level is associated with poor prognosis and can promote the growth and metastasis of lung adenocarcinoma by inducing epithelial-mesenchymal transformation." (PMID 37081097, 2023). "In the COSMIC database, KRT6A c.745T>C mutation is considered pathogenic and has been described in various cancers, including adenocarcinoma of lung." (PMID 35884495, 2022). "More importantly, high KRT6A levels in lung adenocarcinoma is associated with an unfavorable patient prognosis, and KRT6A promotes the growth and metastasis of lung adenocarcinoma through inducing the epithelial-mesenchymal transition." (PMID 34235156, 2021). "The high KRT6A concentration was reported in the analysis of non-small-cell lung cancer (NSCLC) and lung adenocarcinoma (LADC) and is associated with lymph node metastasis and advanced T stage cancer." (PMID 39000463, 2024). "The prognosis of patients with lung adenocarcinoma was significantly affected by six genes (KRT6A, VEGFC, KRT14, KRT17, SNORA12, and KRT81) related to FSTL3." (PMID 38240936, 2024). "In the prognostic analysis of progression-free interval (PFI), CYP4B1 (p = 6.40e-05) and KRT6A (p = 0.0111) had the highest impact on PFI in patients with lung adenocarcinoma, and FAM83A had a higher impact on PFI in KIRC (p = 0.0002052)." (PMID 37081097, 2023). "High expression of KRT6A (HR = 1.125, 95%CI = 1.047–1.207) and FAM83A (HR = 1.288, 95%CI = 1.138–1.457) was associated with poor DSS of lung adenocarcinoma, while CYP4B1 had the opposite effect on lung adenocarcinoma." (PMID 37081097, 2023). "In the prognostic analysis of disease-free interval (DFI), CYP4B1 (p = 0.003) and FAM83A (p = 0.003) had the highest effect on the disease-free progression of lung adenocarcinoma, while KRT6A (p = 0.046) had a higher effect on BRCA." (PMID 37081097, 2023). "In the prognostic analysis of disease-specific survival (DSS), CYP4B1 (p = 0.000249), FAM83A (p = 5.69E-05), and KRT6A (p = 0.001235) had the highest effect on the disease-specific survival of lung adenocarcinoma patients." (PMID 37081097, 2023). "KRT6A protein inhibits the proliferation, migration and invasion abilities of lung adenocarcinoma cells, and high expression of KRT6A protein is a predictor of good prognosis in patients with lung adenocarcinoma." (PMID 36817446, 2023). "KRT6A expression was significantly higher in lung adenocarcinoma (LUAD) and lung squamous cell carcinoma (LUSC) than normal tissues." (PMID 34235156, 2021). "Interestingly, using OS, DSS, DFI, and PFI related univariate Cox regression analysis in various tumors, we found that FAM83A, CYP4B1, and KRT6A had the most significant impact on the survival and progression of lung adenocarcinoma." (PMID 37081097, 2023). "High expression of KRT6A (HR = 1.075, 95% CI = 1.017–1.137) and FAM83A (HR = 2.436, 95% CI = 1.522–3.898) were associated with poor PFI of KIRC, while CYP4B1 (HR = 0.874,95% CI = 0.819–0.934) had the opposite effect on lung adenocarcinoma." (PMID 37081097, 2023). "Firstly, in the analysis of overall survival (OS), FAM83A (p = 2.06e-07), KRT6A (p = 1.22e-07), and CYP4B1 (p = 6.72e-05) had the most significant effect on the overall survival of patients with lung adenocarcinoma." (PMID 37081097, 2023). "MRNA expression levels of TIMP1, S100P, HMMR, F2RL1, KRT6A, and SLC2A1 were significantly increased in lung adenocarcinoma cell lines compared to16HBE, which were consistent with our bioinformatics analysis results." (PMID 35830566, 2022).
lung adenocarcinoma (continued). "Interestingly, another study confirmed our finding by showing that KRT6A inhibits the proliferation and invasion of lung adenocarcinoma cells, and high expression of KRT6A protein may be a prognostic marker for patients with lung adenocarcinoma." (PMID 34235156, 2021). "KRT6A is a member of the cytokeratin gene family, and recently it was reported that ectopic SOX2 over-expression up-regulated the KRT6A mRNA level in a lung adenocarcinoma cell line." (PMID 21304604, 2011). "Knocking down keratin 6A has been found to inhibit cell proliferation, migration, and colony formation ability while not significantly impacting cell viability in lung adenocarcinoma cell cultures." (PMID 38612418, 2024). "Concurrently, we will delve into the interactions between FSTL3 and other pertinent genes, such as KRT6A, VEGFC, KRT14, KRT17, SNORA12, and KRT81, to enhance our understanding of its role in lung adenocarcinoma progression and to pinpoint novel therapeutic targets." (PMID 38240936, 2024). "Furthermore, KRT6A is recognized for its involvement in cell migration and the epithelial–mesenchymal transition (EMT) process across various cancer types, such as lung adenocarcinoma, colorectal, and pancreatic cancer." (PMID 39456519, 2024). "High expression of KRT6A (HR = 1.108, 95%CI = 1.004–1.223) and FAM83A (HR = 1.227, 95%CI = 1.074–1.402) had a poor prognostic progression of BRCA and lung adenocarcinoma, while CYP4B1 had the opposite effect on lung adenocarcinoma (HR = 0.860, 95%CI = 0.778–0.950)." (PMID 37081097, 2023). "In addition, KRT6A promoted EMT and cancer stem cell transformation in lung adenocarcinoma, which is in line with our observation." (PMID 37315289, 2023). "Published data indicates that KRT6A, which is not normally expressed in the human bronchial epithelium, is also markedly upregulated in patients with squamous cell carcinoma of the lung, and in patients with adenocarcinoma of the lung." (PMID 23593124, 2013).
pachyonychia congenita (17 papers, 2008 to 2026). Pachyonychia congenita (PC) is a rare genodermatosis predominantly featuring painful palmoplantar keratoderma, thickened nails, cysts and whitish oral mucosa. "Beyond oncology, mutations in KRT6A underlie pachyonychia congenita, and its dysregulation contributes to epidermal hyperproliferative disorders such as psoriasis." (PMID 41648000, 2026). "Previous studies have shown that statins effectively reduce Keratin 6A (KRT6A) gene promoter activity, leading to their use as a first-line treatment for pachyonychia congenita, a rare skin disorder linked to KRT6A." (PMID 40312750, 2025). "In clinical contexts, specific KRTs, including KRT17 and KRT6A, are associated with keratinization disorders such as epidermolytic hyperkeratosis, ichthyosis, and pachyonychia congenita." (PMID 39201815, 2024). "KRT6A encodes for keratin 6A and involved in wound healing; defects in this gene primarily leads to hypertrophic nail dystrophy (pachyonychia congenita 3 and pachyonychia congenita 1)." (PMID 31272500, 2019). "Pachyonychia congenita (PC) is a rare hereditary condition affecting keratinization, which results from an underlying genetic mutation in one of the five keratin genes: KRT6A, KRT6B, KRT6C, KRT16, or KRT17." (PMID 40686559, 2025). "KRT6A and KRT6B are associated with pachyonychia congenita, as well as renal carcinoma and breast cancer progression." (PMID 29069744, 2017). "Pachyonychia congenita (PC, OMIM #167200, #167210, #615726, #615728, and #615735) is a rare autosomal dominant disorder caused by keratin gene mutations in KRT6A, KRT6B, KRT6C, KRT16 or KRT17." (PMID 34724947, 2021).